RAB32 (RAB32, member RAS oncogene family)
Description:
The small GTPases Rab are key regulators of intracellular membrane trafficking, from the formation of transport vesicles to their fusion with membranes. Rabs cycle between an inactive GDP-bound form and an active GTP-bound form that is able to recruit to membranes different set of downstream effectors directly responsible for vesicle formation, movement, tethering and fusion. Also acts as an A-kinase anchoring protein by binding to the type II regulatory subunit of protein kinase A and anchoring it to the mitochondrion. Also involved in synchronization of mitochondrial fission. Plays a role in the maturation of phagosomes that engulf pathogens, such as S.aureus and M.tuberculosis. Plays an important role in the control of melanin production and melanosome biogenesis. In concert with RAB38, regulates the proper trafficking of melanogenic enzymes TYR, TYRP1 and DCT/TYRP2 to melanosomes in melanocytes (By similarity). Stimulates phosphorylation of RAB10 'Thr-73' by LRRK2.
Synonyms: PARK26
Tractability: Small molecule: a structure with a bound ligand is known. PROTAC: ubiquitination databases record sites on it; its protein half-life has been measured.
Gene: Protein-coding gene on chromosome 6 (146,543,825 to 146,554,964, forward strand). Ensembl gene ENSG00000118508.
Subcellular location: Mitochondrion; Mitochondrion outer membrane; Cytoplasmic vesicle, phagosome; Cytoplasmic vesicle, phagosome membrane; Melanosome; Melanosome membrane
Subcellular location (Human Protein Atlas): Cytosol
Pathways (Reactome):
Metabolism of proteins: RAB geranylgeranylation
Vesicle-mediated transport: RAB GEFs exchange GTP for GDP on RABs
Gene Ontology:
Molecular function: AP-1 adaptor complex binding; AP-2 adaptor complex binding; AP-3 adaptor complex binding; BLOC-2 complex binding; G protein activity; GTP-dependent protein binding; GTPase activity; protein binding; GTP binding
Biological process: antigen processing and presentation; endosome to melanosome transport; melanosome assembly; mitochondrion organization; phagosome maturation; protein localization to membrane; melanosome organization; intercellular transport; vesicle-mediated transport
Cellular component: early endosome; early endosome lumen; endoplasmic reticulum; melanosome; melanosome membrane; membrane; mitochondria-associated endoplasmic reticulum membrane contact site; mitochondrial outer membrane; mitochondrion; phagocytic vesicle; cytosol; trans-Golgi network; cytoplasmic vesicle; Golgi apparatus; phagocytic vesicle membrane; vesicle
Genetic constraint (gnomAD): Loss-of-function variants: 19 observed, 20.82 expected, observed/expected ratio (o/e) 0.91, 90% interval 0.64 to 1.34. The upper end of that interval is the gene's LOEUF score, 1.34, which puts it in group 5 of 6, group 1 being the genes least tolerant of losing a copy. Missense variants: 288 observed, 295.49 expected, observed/expected ratio (o/e) 0.97, 90% interval 0.88 to 1.08. Synonymous variants: 115 observed, 116.8 expected, observed/expected ratio (o/e) 0.98, 90% interval 0.85 to 1.15.
Homologues: Orthologues: chimpanzee RAB32 (99% identical), dog RAB32 (91% identical), pig RAB32 (91% identical), zebrafish rab32a (73% identical), guinea pig RAB32 (72% identical), zebrafish rab32b (45% identical). Paralogues in human: RAB38 (62% identical), RAB29 (48% identical), RAB5C (32% identical), RAB35 (32% identical), RAB10 (32% identical), RAB11A (32% identical), RAB13 (32% identical), RAB31 (32% identical), RAB6A (32% identical), RAB6B (32% identical), RAB22A (31% identical), RAB7A (31% identical), and 56 more.
Diseases named in the same sentence as RAB32 in open-access papers:
RAB32 is named in the same sentence as 54 diseases in open-access papers, as found by Europe PMC text mining. Sharing a sentence is not in itself a finding about the gene and the disease. The quoted sentences say what the papers report.
Parkinson disease (10 papers, 2023 to 2025). A progressive degenerative disorder of the central nervous system characterized by loss of dopamine producing neurons in the substantia nigra and the presence of Lewy bodies in the substantia nigra and locus coeruleus. "A recently discovered gene associated with familiar Parkinson's disease (PD), i.e. RAB32, has been suggested as susceptibility gene in other neurodegenerative syndromes." (PMID 40542608, 2025). "The RAB32 p.Ser71Arg variant is a novel cause of monogenic Parkinson's disease (PD), for which detailed phenotypic information is currently scarce." (PMID 41103171, 2025). "Pathogenic mutations in other Parkinson’s disease genes, including Rab32 and VPS35, also enhance LRRK2 signaling, underscoring the importance of understanding how upstream cellular processes regulate LRRK2 activation." (PMID 41332754, 2025). "Candidates for engaging these pathways in the context of Parkinson’s disease pathogenesis include risk genes such as Rab32 and VPS35 that are known to activate LRRK2 and VPS13C that promotes the repair of damaged lysosomes." (PMID 41332754, 2025). "Within the RAB protein family, RAB32 has also been implicated in late-onset Parkinson’s disease, showing reduced penetrance; notably, RAB32 is phosphorylated by LRRK2." (PMID 41179085, 2025). "This is a statistical estimate of the relative probability that Parkinson's disease and the RAB32 Arg71 allele are inherited together, and is significant for a single marker test." (PMID 38614108, 2024). "Next, we examined the association of RAB32 Ser71Arg with Parkinson's disease risk in each case–control series." (PMID 38614108, 2024). "Analysis of exome sequencing data identifies a missense variant in RAB32 associated with high risk of familial Parkinson’s disease." (PMID 38858457, 2024). "The findings of our genetic and clinical analyses showed that the RAB32 variant Ser71Arg cosegregates with Parkinson's disease in three families; an additional 13 unrelated heterozygotes were identified in case–control analyses." (PMID 38614108, 2024). "The discovery of RAB32 Ser71Arg also suggests several genetically inherited causes of Parkinson's disease originated to control intracellular immunity." (PMID 38614108, 2024). "Together with Rab38/38 and the retromer complex, this interaction regulates signaling pathways associated with LRRK2 activation; furthermore, a missense mutation of Rab32 has been linked with Parkinson’s disease (PD)." (PMID 37566051, 2023). "Our epigenome-wide association study of early Parkinson’s disease provides evidence for methylation changes across different peripheral immune cell types, highlighting monocytes and the RAB32 locus." (PMID 37903812, 2023). "RAB32 Ser71Arg is a novel genetic risk factor for Parkinson's disease, with reduced penetrance." (PMID 38614108, 2024). "Given the shared ancestral haplotype of affected probands with RAB32 Ser71Arg, and their dispersed geographical origin, we anticipate more heterozygotes with this pathogenic variant can be identified through genotyping array data that has already been generated in GWAS of Parkinson's disease." (PMID 38614108, 2024). "While each gene linked to Parkinson's disease compromises the age-associated viability of dopaminergic neurons in the substantia nigra, RAB32 indicates that several of these proteins might have a more intimate synergistic relationship to control pathogen growth in immune cells." (PMID 38614108, 2024). "RAB32’s role in regulating LRRK2-mediated late endosomal trafficking relates to Parkinson’s disease pathogenesis." (PMID 41256702, 2025). "As LRRK2 kinase inhibitors are being trialled as a disease-modifying therapy in Parkinson's disease, further work is needed to establish their potential in RAB32 Ser71Arg Parkinson's disease." (PMID 38614108, 2024). "We subsequently genotyped RAB32 Ser71Arg in population-matched individuals including 2604 unrelated people with Parkinson's disease." (PMID 38614108, 2024).
Parkinson disease (continued). "A total of 19 coding substitutions were identified in RAB32 in the AMP-PD dataset, including two stop mutations, but only Ser71Arg was associated with Parkinson's disease (unadjusted χ2 test 4·9, p=0·026)." (PMID 38614108, 2024). "In most of our RAB32 Ser71Arg heterozygotes, tremor was the initial symptom, and Parkinson's disease onset, clinical variability, and progression were consistent with typical late-onset Parkinson's disease." (PMID 38614108, 2024). "RAB32 Ser71Arg most likely has an important role in the pathogenesis of Parkinson's disease." (PMID 38614108, 2024). "Hence, RAB32 is a nexus that unites at least four major gene discoveries for familial and seemingly sporadic Parkinson's disease." (PMID 38614108, 2024). "Eight RAB32 Ser71Arg heterozygotes were subsequently identified by bioinformatic analysis across four clinicogenomic databases, of whom four individuals of White, North American, or European descent with parkinsonism were identified via the AMP-PD database (US1, US2, US3, and US4)." (PMID 38614108, 2024). "No studies were found describing genetic variability in RAB32 in Parkinson's disease or parkinsonism." (PMID 38614108, 2024). "In mouse melanocytes, which express high levels of Rab38, Rab32, and Rab29, knockdown (or CRISPR knockout) of Rab38, but not Rab32 or Rab29, decreases phosphorylation of multiple LRRK2 substrates, including Rab10 and Rab12, by both endogenous LRRK2 and exogenous Parkinson’s disease-mutant LRRK2." (PMID 37625589, 2023).
leprosy (9 papers, 2016 to 2024). Leprosy is a chronic infectious disease affecting primarily the skin and peripheral nervous system. "In that analysis we identified a promoter variant in RAB32, rs34271799, with suggestive evidence of association with leprosy risk in Malawi and Mali (pMALAWI = 0.0023, pMALI = 0.0034, pCOMBINED = 6.00 × 10−5; OR = 0.42, 95%CI = 0.28 − 0.64, S7 Fig)." (PMID 36121873, 2022). "In addition to their association with leprosy, RAB32 susceptibility has also been linked to PD and CD." (PMID 38440733, 2024). "In addition, genetic evidence indicate a possible role of Rab32 in controlling leprosy, a disease caused by Mycobacterium leprae in humans, suggesting that a Rab32-dependent pathway can also act as a host defense pathway in humans." (PMID 27645564, 2018). "RAB32 regulates autophagy, phagocytosis, and mitochondrial functions in PD, suggesting a similar role in leprosy." (PMID 38440733, 2024). "RAB32 and RAB38 have been shown to mediate phagosome restriction of intracellular pathogens, notably Mycobacterium leprae, the causative agent of leprosy." (PMID 34397087, 2021). "Moreover, signals of DNase‐seq, H3K4me3 ChIP‐seq, or H3K27ac ChIP‐seq were observed in skin or PBMCs in SNPs among the previously identified known leprosy loci, including loci that EGR2, TNFSF15, RAB32, and NOD2 located in." (PMID 38020709, 2023).
melanoma (7 papers, 2017 to 2025). A malignant, usually aggressive tumor composed of atypical, neoplastic melanocytes. "Upregulated expression of some endosomal–lysosomal-associated genes controlling melanogenesis (e.g., RAB32, RAB38, RAB27A, and RAB33) has been observed in melanoma cells and melanoma patient samples." (PMID 41155412, 2025). "Silencing of the BLOC-3 subunits Hps1 and Hps4 results in the mislocalization of Rab32 and Rab38 and a reduction in pigmentation in a melanoma cell line." (PMID 28438206, 2017). "Based on our findings, we discuss the meaning of the Rab32/38-dependent and -independent Tyr transport pathways in melanoma cells and suggest restricting the use of melanoma cells as a model for investigating the mechanism of melanogenic enzyme transport in melanocytes." (PMID 36430618, 2022). "Our findings indicate a difference between the Tyr transport mechanism in melanocytes and B16-F1 cells in terms of Rab32/38-dependency and a limitation in regard to using melanoma cells as a model for melanocytes, especially when investigating the mechanism of endosomal Tyr transport." (PMID 36430618, 2022). "In the present study, we focused on B16-F1 melanoma cells and established several KO cells for key factors in melanogenesis, i.e., Tyr, Hps4, Rab27A, and Rab32/38, to determine whether the mechanisms of melanogenesis in melanocytes are retained in B16-F1 cells." (PMID 36430618, 2022). "In contrast, B16-F10 mouse melanoma cells (“B16 cells”) produce melanosomes, indicating that pathways of LRO biogenesis are active and express high levels of endogenous Rab32, Rab38, and LRRK2." (PMID 37625589, 2023). "In agreement with the previous studies on RAB32 and LRMDA, we could observe a decrease in pigmentation in RAB32 CRISPR/Cas9 knock-out human melanoma MNT1 cells, as well as in a previously characterised LRMDA knock-out MNT1 cell line." (PMID 39975051, 2025). "Rab38 but not Rab32 or Rab29 drives pericentriolar recruitment of exogenous kinase-active LRRK2 in B16 melanoma cells." (PMID 37625589, 2023). "In B16-F10 mouse melanoma cells, Rab38 drives LRRK2 membrane association and overexpressed kinase-active LRRK2 shows striking pericentriolar recruitment, which is dependent on the presence of endogenous Rab38 but not Rab32 or Rab29." (PMID 37625589, 2023). "In addition, melanoma cells typically display enhanced secretion activity of extracellular vesicles (EVs) and melanosomes, which may be significantly augmented by the upregulation of RAB27A, RAB32, RAB33A, and RAB38." (PMID 41155412, 2025).
glioblastoma (4 papers, 2023 to 2024). The most malignant astrocytic tumor (WHO grade IV). "Previous studies have demonstrated that Rab32 facilitates the migration and invasion of glioblastoma cells by modulating ERK/Drp1-mediated mitochondrial fission." (PMID 38388913, 2024). "The purpose of this study was to investigate the expression and function of RAB32 in glioblastoma (GBM)." (PMID 39668831, 2024).
Salmonella Infections (4 papers, 2018 to 2025). Infections with bacteria of the genus SALMONELLA. "Withal, we provide possible further downstream effects of proteolytic modification of Rab32 and deepen the knowledge about mechanisms of Salmonella infection." (PMID 33426511, 2021). "In this mini-review we discuss the findings that led to the identification of the Rab32 host defense pathway in the context of Salmonella infections, evidence of its involvement in controlling other intracellular pathogens and the role of Rab32 in other cellular trafficking processes." (PMID 27645564, 2018). "Upon Salmonella infection, MCT1 and MCT4 transport itaconate into SCV facilitated by RAB32." (PMID 41298379, 2025). "Although RAB32 interacts with IRG1 more robustly upon bacterial infection, the association between MCT1/4 and RAB32 has already existed in the absence of bacterial infection, which was not strengthened following Salmonella infection." (PMID 41298379, 2025).
Chronic Myeloid Leukemia (3 papers, 2019 to 2025). "As a tumour suppressor, miR-141-3p inhibits cell proliferation, migration, and invasion in non-small-cell lung cancer, in chronic myeloid leukaemia by targeting RAB32, and in triple-negative breast cancer by suppressing the Wnt/β–catenin signalling pathway." (PMID 40407536, 2025). "In chronic myeloid leukemia, microRNA-141-5p acts as a tumor suppressor by downregulating RAB32." (PMID 34712334, 2021).
colorectal cancer (3 papers, 2018 to 2022). A primary or metastatic malignant neoplasm that affects the colon or rectum. "Therefore, YQ456 affects multiple functions of Rab7 and Rab32 by targeting MYOF, thereby preventing colorectal cancer progression." (PMID 33634965, 2021). "In summary, the present data demonstrated that Rab32 in CD11c+ cells protects against the development of DSS‐induced colitis by preventing bacterial invasion and suggested that Rab32 might contribute to the pathogenesis of human IBD and IBD‐related colorectal carcinoma." (PMID 30338217, 2018).
glioma (3 papers, 2022 to 2024). A benign or malignant brain and spinal cord tumor that arises from glial cells (astrocytes, oligodendrocytes, ependymal cells). "Collectively, these results suggest that RAB32 expression plays a critical role in the malignant development of glioma, possibly underscoring its association with poor prognosis." (PMID 39668831, 2024). "Despite a substantial body of research highlighting the significance of RAB32 in tumorigenesis, the precise biological functions and molecular mechanisms underlying its role in gliomas remain elusive." (PMID 39668831, 2024). "Survival analysis showed that high expression of RAB32 was an independent risk factor for overall survival in glioma patients." (PMID 39668831, 2024). "This investigation has established the potential of RAB32 as a diagnostic indicator for glioma prognosis, while also indirectly elucidating its influence on cell signaling pathways through gene set enrichment analysis (GSEA)." (PMID 39668831, 2024). "Then, to further verify the prognostic effect of RAB32 on glioma patients, receiver operating characteristic (ROC) curves were generated based on two databases, and the diagnostic value of RAB32 in glioma was evaluated according to the area under the curve (AUC)." (PMID 39668831, 2024). "We next analyzed RAB32 expression in gliomas of varying grades and grouped gliomas based on diverse molecular pathological indices using the CGGA mRNA seq_693 dataset and TCGA mRNA seq_702 dataset." (PMID 39668831, 2024). "Knocking down the expression of the RAB32 gene significantly inhibited the proliferation, migration and invasion of glioma cells." (PMID 39668831, 2024). "Our investigation of glioma cell and tissue microarrays reveals a significant upregulation of Rab32 in glioma specimens, which demonstrates a positive correlation with tumor grade and unfavorable patient prognosis." (PMID 39668831, 2024). "The mRNA and protein levels of RAB32 were examined in glioma and normal brain tissues using multiple databases and western blotting assays." (PMID 39668831, 2024). "Previous experiments established that glioma U87 cells exhibited relatively high expression levels of RAB32." (PMID 39668831, 2024). "This study represents the first comprehensive exploration into the biological functions of RAB32 in gliomas and its correlation with patient prognosis." (PMID 39668831, 2024). "Our findings provide compelling evidence that RAB32 plays a pivotal role in glioma development, thus identifying it as a novel therapeutic target for this aggressive cancer." (PMID 39668831, 2024). "Our data revealed a significant correlation between the expression levels of immune checkpoint molecules (CD274, CTLA4, HAVCR2, LAG3, PDCD1, PDCD1LG2, TIGIT, and SIGLEC15) and RAB32 in high-grade gliomas (HGG)." (PMID 39668831, 2024). "To determine the potential role of Rab32 in the aggressiveness of glioma, we evaluated the effect of Rab32 in the migration and invasion of GBM cells, U87 and U251." (PMID 36922509, 2023). "Our analysis on clinical samples showed that the expression level of Rab32 is high in glioma tissue, and positively correlated with tumor grade and poor prognosis." (PMID 36922509, 2023). "We also evaluated the protein levels of Rab32 in a series of clinical specimens, which included 31 glioma tissues (21 cases of GBM and 10 cases of grade 2–3) and 4 normal peri-tumor tissues, by both immunohistochemistry and western blot analysis." (PMID 36922509, 2023). "Kaplan–Meier plots demonstrated that the high level of Rab32 expression was correlated with poor overall survival of glioma patients." (PMID 36922509, 2023). "We further investigated the correlation between Rab32 expression and the survival of patients with glioma based on these databases." (PMID 36922509, 2023).